CD276 (CD276 molecule)
Diseases named in the same sentence as CD276 in open-access papers (continued):
Sharing a sentence is not in itself a finding about the gene and the disease.
tumor (continued). "Several research groups have proposed CD276 as a UC tumor marker compared with normal tissue." (PMID 35052695, 2021). "CD276 CAR-T showed stronger anti-tumor activity when targeted at tumor cells expressing PD-L1." (PMID 33842369, 2021). "Therefore, we aimed to understand the relevance of CD276 in tumor-macrophage interaction by employing a 3D spheroid coculture system with human cells." (PMID 34290311, 2021). "For example, CD276 (B7-H3) plays a role in down-regulating T-cells involved in tumor immunity." (PMID 33033253, 2020). "As this subpopulation of CD276+CECs and changes therein are likely to reflect better potential effects on tumor vasculature than the total number of CECs, further investigation on the frequency of these cells and their association with outcome in patients with cancer is warranted." (PMID 31948091, 2020). "CD276 expression was also detected in the membrane of tumor cells." (PMID 31998416, 2020). "However, HLA-related gene expression promotes immune responses to clear tumors, while immune checkpoint genes (PDL1, CTLA4, TIM-3, and CD276) suppress immune responses and facilitate tumor proliferation and metastasis." (PMID 33391355, 2020). "Similarly, another study reported that tumoral B7-H3 (CD276) overexpression was correlated with high tumor-infiltrating cytotoxic lymphocytes." (PMID 33092083, 2020). "Furthermore, CD276 high expression and SOCS3 low expression in HCC tissue were significantly associated with high Edmondson grading (P=0.021) and age, tumor size (P=0.026, 0.041), respectively." (PMID 32742491, 2020). "Moreover, we further observed a significant increase in vascular expression of CD276 in ACC cases with more aggressive tumor features (advanced T stage and ENSAT stage), which is consistent with a previous report on distinct cancer types." (PMID 31998416, 2020). "An interesting feature of these data is that, since the Nutlin-3 class of drugs can induce immune blockade receptors PD-L1 and CD276, this might produce an oncogenic effect of the drug in vivo by attenuating T-cell killing of tumor cells." (PMID 32874188, 2020). "CD276 can discriminate between tumor derived and normal CECs (circulating endothelial cells)." (PMID 31948091, 2020). "Increasing data suggest that inhibition of CD276 may suppress tumor growth, and CD276-targeted therapy has shown broad tumoricidal and antimetastatic activity in vivo." (PMID 31998416, 2020). "Among these, CD276 is one of the representative novel targets in tumour immunotherapy." (PMID 29700419, 2018). "In tumour cells, CD276 could reprogram glucose metabolism to benefit growth by ROS-mediated stabilization of HIF-1α17." (PMID 29700419, 2018). "Despite the majority of studies on CD276 and cancer emphasize the paradox immunological role of CD276, several studies showed that CD276 can regulate tumor progression and chemosensitivity by targeting with signaling pathways involved in non-immunological systems." (PMID 27329595, 2016). "And restoration of CD276 completely abrogated the tumor suppressor role of miR-187." (PMID 27329595, 2016). "In contrast, decreased CD276 could reduce immune-suppressive effects by tumor cells." (PMID 40452017, 2025). "Moreover, 71% of malignancies exhibited CD276 expression in more than 25% of tumor cells." (PMID 40801642, 2025). "Additionally, CD276 expression was elevated in tumor tissue compared with normal brain tissue." (PMID 39928563, 2025). "However, post-NT, CD276+ tumor cells still appeared in the NCT group but were reduced significantly in the post-NICT group, while CD16+ NK cells could be observed in the remaining tumors of the NCT and NICT groups." (PMID 39076970, 2024). "Moreover, tumor burden of CD276 wKO mice was substantially lagged behind and reduced." (PMID 38561369, 2024).
tumor (continued). "Additionally, CD276, also known as B7-H3, a member of the B7 family of transmembrane surface molecules, demonstrated a significant expression, with a tenfold increase noted in 44% of the tumor samples." (PMID 38979413, 2024). "However, significant anti-tumor activity without associated toxicity has been demonstrated in preclinical studies using therapeutic strategies targeting CD276." (PMID 39367484, 2024). "In addition, levels of NT5E and CD276 were positively associated with tumor grades, but not other clinicopathological characteristics; notably, tumors from elderly patients expressed higher levels of CD276." (PMID 39911580, 2024). "Finally, because the functions of CD276 in normal cells, such as immune cells, remain largely unknown, the consequences of off-tumor CD276 targeting in normal cells will need careful monitoring moving forward." (PMID 38019654, 2023). "In conclusion, a range of studies have collectively shown that the expression of CD276 in different types of cancer can be regulated by numerous interconnected factors, although the function and potential molecular mechanism of CD276 in tumor progression requires further study." (PMID 36717836, 2023). "In addition, CD276 expression in the fibroblasts of TME is highly associated with the ferroptosis gene signature and poor HNSCC survival, suggesting its suppressive roles in tumor immunity." (PMID 36983005, 2023). "Therefore, little is known if in human tumor cells an outside-in signaling through CD276 may contribute to the pathology of cells affected." (PMID 35563359, 2022). "However, cancer therapy targeting CD276 may be effective in the treatment of slow proliferating tumor cells." (PMID 35563359, 2022). "The evasion of tumor cells from immunorecognition was associated with elevated expression of immune checkpoint molecules such as programmed cell death-1 (PD-1, CD279), its ligand PD-L1 (CD274), cytotoxic T-lymphocyte associated protein-4 (CTLA-4, CD152), or the cell surface molecule B7-H3 (CD276)." (PMID 35628262, 2022). "However, tumor cell migration and invasion are substantially reduced when CD276 is silent." (PMID 36741734, 2022). "Additionally, CD276+ fibroblasts can be used to promote tumor progression and metastasis." (PMID 34367975, 2021). "Therefore, in this study, we aimed to understand whether CD276 modulates macrophage recruitment in a 3D tumor spheroid with human macrophage coculture system." (PMID 34290311, 2021). "In addition to tumor cells, our data also provide insights in CD276 function on macrophages." (PMID 34290311, 2021). "Recent studies have shown that CD276 and B7-H4 have a co-inhibitory role on T-cells, participating in tumor cell immune evasion, whose overexpression has a significant relationship with poor prognosis in tumor patients, which was consistent with the prognostic value of COL1A1." (PMID 33850663, 2021). "According to our tumor data, CD276 could be an upstream regulator for PAI-1." (PMID 34290311, 2021). "In addition, the relationship between smoking and the efficacy of anti-PD-1/PD-L1 therapy may also be related to the status of tumor-infiltrating lymphocytes (TILs) and other immune modulators such as B7-H3 (CD276)." (PMID 31959178, 2020). "Furthermore, CD276 is overexpressed on several other tumors—such as pancreatic ductal adenocarcinoma (PDAC), prostate cancer, ovarian cancer, lung cancer, and clear cell renal carcinoma—and on tumor-associated vasculature and stroma fibroblasts." (PMID 32916883, 2020). "Depletion of CD276 improved TAM MHC-II expression, increased cytotoxic CD8+ T cell infiltration, and reduced tumor growth in a mouse BC model." (PMID 40177538, 2025). "The stiff subtype exhibited significantly increased tumor mutual burden and T cell follicle helper cell levels compared with the soft subtype, along with the expression of CTLA4, CD276, CD47, and TNFRSF25." (PMID 40277910, 2025).
tumor (continued). "The upregulation of B7-H3 in the tumor vascular endothelium correlated with more advanced ccRCC grade and tumor-node-metastasis (TNM) stage and was positively associated with microvessel density (MVD), supporting the notion that CD276 may play a crucial role in angiogenesis." (PMID 40801642, 2025). "The type I transmembrane protein B7-H3 (CD276), an immune checkpoint molecule belonging to the B7 family, is abundantly expressed on cancer cells and activated, tumor-infiltrating immune cells." (PMID 41153826, 2025). "Key genes such as CD276, CD70, and CD274, known for their roles in immune modulation and tumor microenvironment influence, were notably divergent." (PMID 40299331, 2025). "Recently, the immune checkpoint molecule B7-H3 (CD276) has emerged as an immunotherapy target in GBM because of its high expression and limited heterogeneity in tumor cells, including GBM cells." (PMID 39928563, 2025). "It is well known that CD276 inhibits the efficacy of CD8+ cytotoxic T cells and drives tumor immune evasion that correlated with a decreased T cell infiltration within the TME53,54." (PMID 40393975, 2025). "In contrast, CD276 and IGFBP1 were primarily expressed in epithelial cells, implying a potential engagement in modulating tumor biological behavior." (PMID 41488652, 2025). "Prompted by the weak dependence on target antigen density of the CD276-directed CAR NK-92 cells, we next studied potential on-target/off-tumor effects." (PMID 40469103, 2025). "Here, we evaluated two CAR-NK-92 cell lines, targeting either CD276 or HER2, and their potential on-target/off-tumor effects in vitro." (PMID 40469103, 2025). "B7-H3 (CD276), a transmembrane protein identified in 2001 as a member of the B7 superfamily, demonstrates tumor-restricted overexpression across multiple malignancies." (PMID 40892295, 2025). "B7-H3 (CD276), an immune checkpoint molecule involved in tumor progression, along with receptors EGFRvIII and IL13Rα2, are highly overexpressed in GBM and associated with worse prognoses, making them attractive therapeutic targets." (PMID 39941829, 2025). "Analyses of bulk RNA-seq of human ccRCC revealed that PDCD1LG2 and CD80 expression were upregulated in ccRCC tumours compared to normal kidney, as was expression of LGALS3, LGALS9, SELL and CD276." (PMID 40473819, 2025). "GBM-derived exosomes also carry B7-H3 protein (CD276), which can impair NK cell cytotoxicity, providing tumor cells with an additional mechanism of immune escape." (PMID 40496868, 2025). "B7H3, also known as CD276, is notably overexpressed in various malignant tumor cells in humans, with extremely high expression rates." (PMID 39847434, 2025). "The systematic characterization of the tumor of the CNS identified HER2, HER3, NECTIN4, TROP2, CLDN6, CLDN18.2, and CD276/B7H3 proteins as potential therapeutic targets." (PMID 40677711, 2025). "B7 homolog 3 (B7-H3) (CD276), a member of the B7 superfamily of immunoregulatory molecules, plays a pivotal role in tumor immunology and cancer progression." (PMID 40002543, 2025). "B7-homologue 3 (B7-H3 or CD276) is a type I transmembrane protein and a member of the B7 family that is expressed on both tumor and immune cells." (PMID 40565299, 2025). "Flow cytometry of dissociated tumor cells stained for NLuc and Ki67 revealed that ~ 75.9% of TNBC cells were successfully infected with CD276 mAb-Exo-AAV and expressed functional cmLumiOpto gene." (PMID 41462289, 2025). "B7-H3 (CD276), initially described as a co-stimulatory molecule, has been identified by numerous authors as a potent suppressor of anti-tumor responses." (PMID 40801642, 2025). "Moreover, ENHO’s negative correlations with other immune checkpoint molecules, such as CD276 (B7-H3) and NT5E (CD73), which are implicated in immune escape by suppressing T-cell activity and promoting regulatory T-cell (Treg) responses, further reinforce its potential anti-tumor role." (PMID 40647442, 2025).
tumor (continued). "To understand the clinical relevance of CD276 in SCLC, we determined expression levels of CD276 on SCLC in different primary patient sample cohorts and tumor cell lines." (PMID 40722088, 2025). "We demonstrated that PRMT5-mediated meR316-ALKBH5 promotes CD276 messenger RNA (mRNA) stability through m6A modification, thereby enhancing CRC tumor immune evasion both in vitro and in vivo." (PMID 39781264, 2025). "Among immunostimulators, CD276, PVR, TNFRSF14, TNFRSF25 and TNFSF9 were also negatively correlated with LAMP3 expression in some tumours." (PMID 38146591, 2024). "We further examined the links between tumor heterogeneity and the expression of NT5E and CD276, finding positive correlations between NT5E or CD276 expression and the degree of homologous recombination deficiency and loss of heterozygosity." (PMID 39911580, 2024). "The differential response of CD276-positive ESCC PSO and CD276-negative NC PSO following iPSC CD276-targeted CAR-NK treatment indicates the on-target effect and the potential off-tumor toxicity of iPSC CD276-targeted CAR-NK in future clinical trials." (PMID 38566988, 2024). "It is therefore worth noting that anti-inflammatory chemokines including CSF1, CD276, VEGFA, and CX3CL1 were upregulated in pedB tumor epithelial cells." (PMID 39482394, 2024). "Further investigation revealed a significant correlation between CD276 and RAB3B in 22 tumor types, highlighting the need for further mechanistic studies." (PMID 38688977, 2024). "The observed changes in the expression of relevant immunosuppressive receptors in CAFs exposed to radiation in vitro (CD276 and CD73), prompted us to explore if such effects occurred also in in vivo tumor models." (PMID 39308864, 2024). "For instance, CAR‐T cells targeting CD276 have shown efficacy in eliminating ESCC, leading to significant tumor reduction and extended survival in murine models." (PMID 39415846, 2024). "When treating with anti-CD276 antibodies, it was observed that CSCs were eliminated by CD8+ T cells, which also inhibited tumor growth and nodal metastasis." (PMID 39335624, 2024). "We then engineered three GAS-Luc2 reporter tumor cell lines expressing immune checkpoints PD-L1, CD155, or B7-H3/CD276." (PMID 38893085, 2024). "When CD276 has been used as a therapeutic target in preclinical studies, including the use of CD276-directed CAR-T cells, significant anti-tumor effects have been observed." (PMID 38637557, 2024). "To explore the correlation between Plek2 knockdown and immunomodulatory molecules, we collected tumor tissues from C57BL/6 mice bearing tumors and extracted RNA for RT-PCR analysis of Cd276, Cd274, and Lgals9 expression." (PMID 39546161, 2024). "CD276 is expressed on CRC cells and on tumor vessels, thereby allowing for a “dual” anticancer effect." (PMID 38410109, 2024). "Key immune checkpoints B7-H3 (CD276), OX40 (TNFRSF4) and TIM3 (HAVCR2) also displayed significantly higher expression (p < 0.05) in some tumor slides." (PMID 39529126, 2024). "To model heterogeneous expression of tumor antigens in an in vivo model, we established bilateral orthotopic xenografts with RH30 FGFR4-KO (right leg) and CD276-KO (left leg)." (PMID 39043633, 2024). "Through RNA-Seq analysis of HNSCC samples (3 tumors and 3 para-carcinoma tissues), we identified 8 pivotal marker genes (PCDH7, CDH2, ITGA3, SEMA7A, TMEM132A, CD276, TMEM2, GPR158) that were overexpressed in tumor specimens." (PMID 38548747, 2024). "The B7 homolog 3 protein (B7-H3, CD276) of the B7 immunoglobulin superfamily, like its cognate member PD-L1, plays a crucial role in regulating tumor immune responses." (PMID 39076970, 2024). "Meanwhile, several important ICP genes, such as CD274, CTLA4, CD276, etc. were highly expressed in the PS1 and PS2 subtypes, indicating an immunosuppressive tumor microenvironment in these patients, and they were more likely to be benefit from ICIs." (PMID 38672082, 2024).
tumor (continued). "In contrast, both FGFR4.28HTM.BBz-CD276.8HTM.BBz and FGFR4.28HTM.28z-CD276.8HTM.BBz BiCisCARs completely eradicated tumors in all mice, and the latter showed a more rapid tumor elimination." (PMID 39043633, 2024). "B7-H3 (CD276), a member of the B7 family similar to PD-L1 and part of the B7-CD28 interaction, aids in tumor immune evasion and metastasis." (PMID 39528800, 2024). "We and others have reported that CD276 is overexpressed on a wide range of human solid tumors, including RMS15–17, and its overexpression is correlated with tumor progression, metastasis, and poor clinical outcome across a variety of malignancies." (PMID 39043633, 2024). "Surprisingly, MCM3 was positively correlated with the expression of several immune checkpoint molecules, such as HMGB1, BTN3A2, CD276, and VEGFA, in almost all of the tumours." (PMID 38698811, 2024). "CD276/B7H3 is a type I transmembrane protein overexpressed in several solid tumors and often correlated with poor survival and higher tumor grade." (PMID 37725435, 2023). "Expression of immunoregulatory proteins such as B7-H3 (CD276) and HHLA2 was shown to be higher than PD-L1 expression, directly proportional to the Gleason score and tumor stage and negatively proportional to the number of CD8+ TILs." (PMID 37738978, 2023). "The ADC constructed with our CD276 mAb and payload monomethyl auristatin F (MMAF) showed high anti-NSCLC cytotoxicity to multiple lines and effective anti-tumor efficacy in both immunocompromised and immunocompetent NSCLC xenograft mouse models." (PMID 37830607, 2023). "We focused on the following tumor-related antigens found in BC: HER2, TROP2, EGFR, CD276, and EpCAM." (PMID 38201595, 2023). "CD276 is correlated with the reduced function of TMJ and BRCA, as well as low tumor-infiltrating lymphocytes (TIL), and it is highly expressed in advanced Pca." (PMID 37366915, 2023). "Based on TCGA HNSCC tumor bulk dataset, patients with HNSCC had higher TIGIT, LAG3, and CD276 expression levels than healthy individuals." (PMID 38096229, 2023). "Our results revealed higher expression of the CD276 and NMB proteins in tumor than in normal tissues, whereas CBX6 was only highly expressed in normal intestinal mucosal tissues." (PMID 37428291, 2023). "By combining CD276-targeted NIR-PIT and anti-PD-L1 therapy, they were able to prevent subcutaneous tumor regrowth and lung metastasis." (PMID 37860012, 2023). "However, CD276 and its exact downstream cascade are still under investigation, and divergent results have been obtained for CD276 on whether it acts as a co-stimulator or co-inhibitor of T cell-mediated immune responses in different tumor types." (PMID 38275375, 2023). "IHC analyses detected T cells in the spleen of Rh4-bearing mice injected with control untransduced T cells (UTD control) and in the spleen of CD276.V-CAR T cells treated mice, suggesting persistence of CAR T cells even after tumor eradication." (PMID 37924157, 2023). "We found that in the PTEN low-expression group, there was a significant decrease in the expression of some immune checkpoints, including CD276, CD274, NRP1, and the TNFRSF family, that are closely involved in immunosuppressive signals in HCC tumor." (PMID 36861063, 2023). "In detail, the OC tumor tissue and PSO showed MSLN expression on some cells, as well as positive expression of MUC1 and CD276." (PMID 38162496, 2023). "In this study, the expression of KIFC1 was positive with immune checkpoints like CTLA4, CD276, and LAG3 in most tumor types." (PMID 38112634, 2023). "In terms of immune checkpoints, the expressions of CTLA4, CD276, CD47 and TNFRSF25 were significantly higher in “stiff tumor”." (PMID 37179366, 2023). "CD276 is a B7 family member related to impaired TMJ and BRCA function and low tumor infiltrating lymphocytes (TILs), and it is closely related to PTEN deficiency." (PMID 37366915, 2023).